TRPV4 (transient receptor potential cation channel subfamily V member 4)
Diseases named in the same sentence as TRPV4 in open-access papers (continued):
Sharing a sentence is not in itself a finding about the gene and the disease.
Hydrocephalus (continued). "In the Tmem67–/– genetic model of communicating hydrocephalus, we have shown that 2 different TRPV4 antagonists inhibit the development of ventriculomegaly." (PMID 32938829, 2020). "Next, quantitative PCR was used to determine potential changes in the gene expression of Trpv4 and Sgk1 that may be modified by hydrocephalus or SI113 treatment." (PMID 37596666, 2023). "These in vivo and in vitro data suggest that targeting TRPV4 activity either directly or indirectly through intracellular TRPV4 regulators may be a viable strategy for the treatment of hydrocephalus." (PMID 37047646, 2023). "On the other hand, TRPV4 agonist treatment exacerbated the hydrocephalus in the affected animals." (PMID 36982349, 2023). "Importantly, we have shown treatment with two structurally distinct TRPV4 antagonists inhibits the progression of hydrocephalus in this model." (PMID 37596666, 2023). "We have shown that SGK1 activity is important for TRPV4 activation during choroid plexus-mediated stimulation of electrolyte and fluid secretion, making this pathway an attractive target in the treatment of homeostatic disorders such as hydrocephalus." (PMID 37596666, 2023). "TRPV4 inhibition alleviates ventriculomegaly in a genetic model of hydrocephalus." (PMID 36068581, 2022). "Additionally, chronic TRPV4 antagonism is effective at reducing symptoms of hydrocephalus in rats, a disease characterised by the abnormal accumulation of CSF." (PMID 34573139, 2021). "The published studies combined with our current data suggest that inhibition of TRPV4 may be a safe and effective treatment for some forms of hydrocephalus." (PMID 32938829, 2020). "We speculate that our findings of TRPV4 antagonist–mediated inhibition of the development of hydrocephalus will be applicable to most forms of the disease and could be used on an as-needed basis." (PMID 32938829, 2020). "This fundamental knowledge suggests the need for additional studies on potential therapies targeting LPA, TRPV4, SPAK, or NKCC1 to reduce hydrocephalus." (PMID 39364470, 2024). "We postulated that despite the lack of significant changes in gene expression, perhaps the abundance and/or phosphorylation of SGK1 and TRPV4, as well as some downstream targets of SGK1, would be changed due to hydrocephalus and/or drug treatment." (PMID 37596666, 2023). "We show compelling evidence that SI113 inhibits SGK1 activity and corresponding TRPV4 activation in the choroid plexus, and that SI113 treatment inhibits the progression of hydrocephalus in a preclinical rodent model." (PMID 37596666, 2023). "Hydrocephalus, commonly found in MKS3, can be the consequence of an imbalance in fluid-electrolyte homeostasis, finely regulated by ion transporters like TRPV4, whose expression is controlled by Sgk1." (PMID 36982349, 2023). "They demonstrated that LPA can act as an agonist of TRPV4 in the choroid plexus and that treatment of their LPA-induced hydrocephalus model with a TRPV4 antagonist ameliorated the ICP and slowed CSF secretion rates." (PMID 36050779, 2022). "PubMed and Google Scholar search terms included: hydrocephalus clinical treatment, non-surgical hydrocephalus treatment, memantine hydrocephalus, acetazolamide hydrocephalus, prevalence of pediatric hydrocephalus, TRPV4 antagonist hydrocephalus, SPAK inhibitor hydrocephalus." (PMID 39364470, 2024). "Lastly, we will highlight the non-surgical interventions used for hydrocephalus treatment, including acetazolamide, memantine, TRPV4 antagonist, NKCC1/SPAK inhibitors." (PMID 39364470, 2024). "The current studies highlight a novel drug target, serum- and glucocorticoid-induced kinase 1 (SGK1) within the TRPV4 pathway and show the efficacy of an inhibitor of SGK1 in the treatment of hydrocephalus in vivo and mechanistically in a human cell line in vitro." (PMID 37596666, 2023).
Hydrocephalus (continued). "We found that total TRPV4 abundance did not change with regards to the previously identified CPe isoforms and glycosylation products in response to hydrocephalus or drug treatment, consistent with the findings in our previous TRPV4 antagonist treatment study." (PMID 37596666, 2023). "TRPV4 could thus act as the molecular link coupling the hemorrhage-mediated LPA elevation to the CSF hypersecretion and ensuing hydrocephalus." (PMID 36068581, 2022). "Two distinct TRPV4 antagonists ameliorate ventriculomegaly in a genetic rat model of severe postnatal hydrocephalus, with no apparent adverse effects on animals." (PMID 32938829, 2020). "The mechanism of action and the role of TRPV4 in the development of hydrocephalus do not appear to be dependent on increased expression of the channel protein, suggesting that the mechanism is, rather, a change in cell surface expression and/or activation." (PMID 32938829, 2020). "Antagonists to the transient receptor potential vanilloid 4 (TRPV4), a gated divalent cation channel highly expressed by choroid plexus, have also been proposed as a treatment for hydrocephalus, but there are no published data supporting the concept." (PMID 26846184, 2016). "Additionally, chronic TRPV4 antagonism reduced cranial dimensions (as a measurement of CSF accumulation) in hydrocephalus rats but not in wild-type controls." (PMID 34573139, 2021). "The authors of the study conclude that activation of TRPV4, but not expression levels, may be altered in neurological diseases with increased CSF secretion, such as hydrocephalus." (PMID 34573139, 2021). "The authors hypothesized that since the systemic delivery of the TRPV4 antagonist did not affect ventricle size in wild-type animals, the increased permeability of the various brain barriers due to the hydrocephalus allowed the drug to reach its target in the choroid plexus." (PMID 36050779, 2022).
ischemic stroke (12 papers, 2013 to 2026). A stroke disorder caused by obstruction of blood flow to the brain, due to thrombotic (local blood clot formation) or embolic (due to a blood clot or other material traveling from another site) event. "Upregulated Trpv4 (log2FC = 1.28), which encoded a Ca2+ channel that mediates Ca2+ influx into the cell during ischemic stroke, exerted injurious effects." (PMID 39224379, 2024). "Studies have shown that activating TRPV4 can help patients who underwent ischaemic stroke to recover by promoting vascular regeneration." (PMID 38697767, 2025). "Overall, our study highlights the efficacy of EA at Shuigou (GV26) and Baihui (GV20) on MCAO mice while proposing a mechanism involving inhibition of the TRPV4 channel to suppress M1 polarization in microglia/macrophages following ischemic stroke in mice." (PMID 38334061, 2024). "TRPV1 or TRPV4 inhibition has been applied in treating ischemic stroke via preserving the BBB permeability in various in vitro and/or in vivo experiments, while TRPV2, the most expressed isoform in human BBB, is much less studied." (PMID 33806707, 2021). "These phase-dependent roles indicate that targeted modulation of TRPV4, particularly through physical therapies, could represent a potential therapeutic strategy to improve outcomes after ischemic stroke." (PMID 41606676, 2026). "Emerging evidence suggests that TRPV4 may function as a modulator in the pathophysiology of ischemic stroke." (PMID 41606676, 2026). "Moreover, vasodilation was nearly abolished by IbTx in the endothelial‐denuded arteries of ischemic stroke rats, suggesting a functional interplay between BKCa and TRPV4 channels in this state." (PMID 40116175, 2025). "TRPM2, TRPV2, and TRPV4 exacerbate neuroinflammation and worsen outcomes in ischemic stroke." (PMID 41399206, 2025). "TRPM2, TRPV2, and TRPV4 exacerbate ischemic stroke, while TRPM8 plays a protective role." (PMID 41399206, 2025). "Decreases LDH activity and MDA, NSE and S100β contents; relaxes the cerebral basilar artery in a dose-dependent manner; up-regulates IP3, PKC, TRPV4, SKca and IKca expression; reduces Ca2+ fluorescence intensity; and ameliorates brain injury in rats with ischaemic stroke." (PMID 35566359, 2022). "The present study suggests that TRPV4 is a promising novel target for treatment of ischemic stroke." (PMID 23459987, 2013). "Therefore, inhibiting TRPV4‐mediated neuroinflammation may be a promising therapeutic strategy for ischemic stroke treatment." (PMID 38334061, 2024). "However, Chen’s research group found that application of TRPV4 agonist may improve the functional recovery from ischemic stroke through increasing angiogenesis and neurogenesis." (PMID 31097691, 2019). "It has been reported that TRPV4 activation by 4α-phorbol 12,13-didecanoate (4α-PDD) in rats promotes the functional recovery from ischaemic stroke by promoting angiogenesis and neurogenesis." (PMID 38697767, 2025). "It appears therefore puzzling that TRPV4 activation using the selective activator 4α-PDD, induced angiogenesis and neurogenesis and thereby contributed to functional recovery from ischemic stroke in mice." (PMID 32974355, 2020). "In the present study, the expression and function of both TRPV4 and BKCa were upregulated in rat MCA after ischemic stroke, although EC‐TRPV4 did not directly activate EC‐BKCa." (PMID 40116175, 2025). "Pre‐incubation with the TRPV4 antagonist, HC‐067047, did not affect the vascular tone of MCAs from sham and ischemic stroke rats (from 65.7 ± 1.9% to 64.9 ± 3.5% and from 62.5 ± 2.8% to 57.7 ± 8.6%, respectively, n = 4) but abolished the GSK1016790A‐induced vasodilation in both groups." (PMID 40116175, 2025).
lung diseases (12 papers, 2016 to 2026). "TRPV4 is a well-recognized mediator of lung function and has also been implicated in various pulmonary disease states, including fibrosis, inflammation, and pulmonary edema formation." (PMID 39451235, 2024). "Dysfunction of TRPV4 is linked to many severe diseases, including edema, pain, gastrointestinal disorders, lung diseases, and inherited neurodegeneration." (PMID 38659239, 2024). "The cation channel TRPV4 has been implicated in lung diseases associated with parenchymal stretch and inflammation or infection." (PMID 32676078, 2020). "TRPV4 has been shown to play a role in lung diseases associated with lung parenchymal stretch or stiffness." (PMID 28523001, 2017). "In summary, ion channels are important in the pathogenesis of inflammatory lung diseases, and the ion channel TRPV4 plays a specific role in mediating lung diseases associated with parenchymal stretch and inflammation or infection." (PMID 28523001, 2017). "The activation of TRPV4 channels has been implicated in pulmonary hypertension, hyponatremia, neurodegenerative skeletal muscle dysplasia, and bone disorders and its inhibition presents a potential therapeutic strategy for pain, gastrointestinal disorders, edema, and lung diseases." (PMID 33981725, 2021). "In the context of lung diseases, TRPV4 is involved in the response of ASM cells to mechanical stress, which has been linked to dysfunction, i.e., hyperreactivity of this tissue." (PMID 38543079, 2024). "This can highlight the critical role of TRPV4 in respiratory physiology and its potential as a therapeutic target in the treatment of lung diseases." (PMID 39408877, 2024). "These functions highlight the importance of TRPV4 in respiratory health and its potential as a therapeutic target in various pulmonary diseases." (PMID 39408877, 2024). "In humans suffering from pulmonary disease and a mouse model, transient receptor potential vanilloid 4 (TRPV4) channel activation contributes to fibrosis." (PMID 28030558, 2016). "However, there is a need for further pharmacologic and clinical studies to fully comprehend the molecular mechanism of TRPV4 in lung disease development." (PMID 38543079, 2024). "However, the primary role of TRPV4 in hypoxic pulmonary vasoconstriction indicates the detriment of TRPV4 inhibition to patients with lung disease." (PMID 33981725, 2021). "However, the roles of TRPV4 in lung diseases are complex, since both protective and deleterious actions have been reported, depending on the models under study." (PMID 35002766, 2021). "In lung diseases, TRPA1, TRPC4, TRPC6, TRPM2, TRPM8, TRPV1, and TRPV4 are the TRP channels most abundantly expressed in lung tissues." (PMID 39408877, 2024). "Therefore, TRPV4 may be a potential target for lung disease pathogenesis." (PMID 28523001, 2017).
lung injury (12 papers, 2016 to 2024). "Based on these data, it is unlikely that TRPV4 inhibition with GSK2798745 will be efficacious as a stand-alone treatment for chlorine-induced acute lung injury." (PMID 38612759, 2024). "Furthermore, TRPV4 is abundantly expressed in pulmonary microvascular endothelial cells, during pulmonary inflammation, TRPV4 is highly expressed and up-regulated in vascular endothelial cells, suggesting that TRPV4 is associated with the development of infection-associated acute lung injury." (PMID 39355841, 2024). "TRPV4 inhibition prevents edema and inflammation, and improves oxygen saturation and pulmonary function in HCl- and Cl2-induced chemical lung injury, suggesting TRPV4 inhibitors as a potential treatment for acute lung injury." (PMID 33981725, 2021). "TRPV4 has been identified recently as an important player in ventilator- and chemical-induced acute lung injury." (PMID 26973533, 2016). "To explore whether the increased TRPV4 protein levels during the demyelinating phase of sciatic nerve injury arise from SCs, we attempted to assess TRPV4 protein levels in SCs after nerve injury." (PMID 33247229, 2020). "If ROS does actively influence bone healing, it would be interesting to investigate, whether macrophages in the bone fracture hematoma also sense mechanical stimuli via mechanosensitive ion channels, such as TRPV4, and also produce ROS as they do in lung injuries." (PMID 33644014, 2021). "The pathogenesis of APAP-mediated acute liver injury involves the activation of TRPV1, TRPV4, TRPC1, TRPM2, and TRPM7 channels, which trigger the influx of Ca2+ into hepatocytes and subsequent cellular damage." (PMID 37569884, 2023). "In acute lung injury, TRP vanilloid 4 (TRPV4)-dependent Ca2+ influx contributes to LPS-induced macrophage activation, a process associated with the calcineurin-NFATc3 pathway." (PMID 34507301, 2021). "It is suggested that after traumatic brain injury, excessive mitochondria-derived H2O2 activates BKCa channels via a TRPV4-dependent pathway in the VSMCs, impairing pressure-induced constriction of cerebral arteries." (PMID 33981725, 2021). "Thus, based on previous work, we hypothesize that LPS causes calcium overload in lung effector cells via the interplay of TRPV4 and IP3R1 in sepsis-induced acute lung injury." (PMID 39355841, 2024). "However, another TRPV4 inhibitor, HC-067047, applied 45 min after lung injury to simulate a clinically more relevant scenario, offered no protection from acute lung injury, suggesting that timing of treatment may be important in the effectiveness of TRPV4 inhibition in preventing IRI." (PMID 38637760, 2024).
colon cancer (11 papers, 2018 to 2024). "The signature we constructed consists of three genes (MCOLN1, TRPM5, and TRPV4), all identified as independent prognostic and risk factors for colon cancer through the multivariate Cox regression model." (PMID 38188686, 2023). "Our results indicated that TRPV4 was upregulated in colon cancer and associated with poor prognosis." (PMID 31189890, 2019). "In this study, we demonstrated that TRPV4 is upregulated in colon cancer and associated with poor prognosis." (PMID 31189890, 2019). "Therefore, in the current study, we aimed to explore the underlying mechanism of TRPV4 controlling metastasis in colon cancer." (PMID 34814869, 2021). "Our recent study has demonstrated that TRPV4 is associated with colon cancer development." (PMID 34814869, 2021). "The role of TRPV4 in colon cancer development and progression takes place through the activation of the AKT signaling pathway and regulation of ZEB1 expression, consequently leading to EMT." (PMID 39517820, 2024). "Consistent with the present findings, we previously reported that knocking down TRPV4 suppressed colon cancer cell growth via PTEN activation, and inhibited invasiveness by blocking ZEB1 signaling." (PMID 36619170, 2022). "Inhibition of TRPV4 suppressed the growth of colon cancer cells by blocking the cell cycle in the G1 phase and inducing apoptosis and autophagic cell death." (PMID 36060694, 2022). "In a recent study, we demonstrated that knocking down TRPV4 in colon cancer cells suppressed their malignant potential by activating PTEN, and decreased their invasiveness via inhibition of ZEB1 signaling." (PMID 36619170, 2022). "Analysis of the data from The Cancer Genome Atlas and the Genotype-Tissue Expression platform also identified TRPV4 as an oncogene and a prognostic marker in colon cancer." (PMID 36619170, 2022). "However, the underlying molecular mechanism of TRPV4 in colon cancer invasiveness is still unknown." (PMID 34814869, 2021). "Our results illustrated that TRPV4 promotes colon cancer progression via inhibition of PTEN signaling." (PMID 34814869, 2021). "Colon cancer cells were transfected with siRNA against TRPV4 or HC067047 (a selective TRPV4 antagonist), TRPV4 full-length plasmid or siRNA against ZEB1, or both, in order to measure cell migration and invasion." (PMID 34814869, 2021). "And we found that TRPV4 silencing or inhibition exhibited an inhibitory role in colon cancer cell migration and invasion, coupled with compromised EMT process, and suppressed AKT activity." (PMID 34814869, 2021). "Contrary to the reported cell death-promoting activity of TRPV4 in certain cancer cells, TRPV4 positively regulates cell survival in human colon cancer in vitro and in vivo." (PMID 31189890, 2019). "In this study, in addition to inducing the dephosphorylation of PTEN, inhibition of TRPV4 expression or activity increased the nuclear localization of PTEN in colon cancer." (PMID 31189890, 2019). "Our data showed that in 86% (86/100) of patients, TRPV4 expression levels in colon cancer were higher when compared to adjacent normal tissues." (PMID 31189890, 2019). "These clinical and biological findings have indicated the potential role of TRPV4 as a proto-oncogene in colon cancer." (PMID 31189890, 2019). "In our study, disruption of TRPV4 silencing-mediated autophagy by knockdown autophagy-related genes increased colon cancer cell viability." (PMID 31189890, 2019). "In the present study, we reported three major findings that allow a better understanding of the role of TRPV4 in colon cancer cells." (PMID 31189890, 2019). "Together, these results suggested that Ca2+-permeable TRPV4 channels are present in colon cancer cells." (PMID 31189890, 2019). "Taken together, these results demonstrated that blocking the activity or expression of TRPV4 inhibited colon cancer cell growth." (PMID 31189890, 2019).